SOX18 (SRY-box transcription factor 18)
Diseases named in the same sentence as SOX18 in open-access papers (continued):
Sharing a sentence is not in itself a finding about the gene and the disease.
lymphangiosarcoma (1 paper, 2025). A malignant neoplasm arising from the endothelial cells of the lymphatic vessels. "In this in vitro study, we investigated the potential therapeutic effect of a small molecule called Sm4, which inhibits SOX18, on lymphatic endothelial and lymphangiosarcoma cells in vitro." (PMID 39791369, 2025). "Despite these limitations, our study provides a foundation for future research on Sox18 as a potential therapeutic target for lymphangiosarcoma cells and a more detailed understanding of its specific tumor biology." (PMID 39791369, 2025). "Our study, demonstrating a reduction in Sox18 expression upon Sm4 treatment in both HDLEC and MO‐LAS, suggests that SOX18 serves as a potential therapeutic target in regulating lymphangiosarcoma and cancer‐induced lymphatic metastasis biology." (PMID 39791369, 2025). "Further studies addressing the limitations mentioned will help advance our understanding of the therapeutic potential of SOX18 inhibition in the management of lymphatic metastasis and lymphangiosarcoma." (PMID 39791369, 2025). "In vivo studies using animal models or patient‐derived samples would provide a more comprehensive understanding of the therapeutic potential of SOX18 inhibition in lymphangiosarcoma treatment and its effects on tumor growth, metastasis, and overall survival." (PMID 39791369, 2025). "Here, we investigated the potential therapeutic effect of inhibiting SOX18 via Sm4 pathway in lymphatic endothelial cells and lymphangiosarcoma cells in vitro to evaluate its role as a treatment target." (PMID 39791369, 2025). "The observed results provide valuable insights into the role of SOX18 and its inhibition in lymphatic endothelial and lymphangiosarcoma cells." (PMID 39791369, 2025). "The diminished migration observed in our study suggests that SOX18 inhibition by Sm4 could impede the growth of lymphangiosarcoma cells and cancer‐related lymphangiogenesis." (PMID 39791369, 2025). "Lymphangiosarcoma is a rare and heterogeneous malignancy, and the response to SOX18 inhibition may vary among different subtypes or individual patients." (PMID 39791369, 2025). "While SOX18 has been broadly studied in various cancers such as skin, stomach, liver, breast, lung, cervical, and ovarian cancer, its role in lymphangiosarcoma remains unexplored." (PMID 39791369, 2025). "In this study, we investigated the expression patterns and functional effects of SOX18 inhibition using Sm4 in HDLEC and lymphangiosarcoma tumor cell line (MO‐LAS)." (PMID 39791369, 2025). "Additionally, our findings reveal that SOX18 inhibition by Sm4 results in a decrease in lymphatic phenotype key markers (PROX1, VEGFR3, and LYVE1), indicating a potential role for SOX18 in promoting cancer‐related lymphangiogenesis as well as lymphangiosarcoma development and progression." (PMID 39791369, 2025).
neuroblastoma (1 paper, 2022). Neuroblastoma (NB) is the most common solid, extracranial childhood tumor. "In particular, overexpression of Sox18 can stimulate MOR gene transcription in human and murine neuroblastoma cells, suggesting that Oprm1 is a downstream target of Sox18 protein." (PMID 36233105, 2022).
ovary carcinomas (1 paper, 2015). "Recently, two studies have been published revealing the high expression of SOX18 not only in blood and lymphatic vessels, but also in nucleus of cancer cells of invasive breast and ovary carcinomas." (PMID 26588701, 2015).
pancreatic carcinoma (1 paper, 2022). "SOX18 is another member of SOX family associated with pancreatic carcinoma, showing a high level of expression in PDAC tissue samples and correlation with poor prognosis." (PMID 35408514, 2022).
papillary thyroid carcinoma (1 paper, 2024). "A dominant negative mutation in the Sox18 gene affects hair follicle development through the silencing of Wnt5a expression, and the overexpression of Sox18 in papillary thyroid carcinoma cells reduces the expression level of active β-catenin." (PMID 39594589, 2024).
Uterine leiomyoma (1 paper, 2017). The presence of a leiomyoma of the uterus. "Using total RNA prepared from our second panel of 26 matched specimens, we confirmed that ESR1, SOX18, CCL5, and PCDH10 but not CALCRL are differentially expressed in uterine leiomyomas or that levels of their expression vary by menstrual phase." (PMID 28637297, 2017).
virus infection (1 paper, 2025). "These newly identified functions of SOX18 underscore its pivotal role in viral infection and provide a mechanistic basis for the virus-induced upregulation of SOX18 at both mRNA and protein levels in infected endothelial cells." (PMID 40894008, 2025). "Disruption of SOX18 or BRG1—genetically or pharmacologically—leads to reduced episome load and attenuated hallmarks of virus infection." (PMID 40894008, 2025).
tumor (46 papers, 2010 to 2026). "Cytoplasmic SOX18 expression is associated with poor patient outcome, and nuclear SOX18 is positively associated with Ki-67 proliferation index, suggesting its role in tumor progression and potential as a prognostic biomarker." (PMID 41268614, 2026). "The strong co-expression of these genes with SOX18 in vascular regions suggests the existence of a spatially restricted signaling network potentially involved in sustaining tumor-associated vasculature." (PMID 41373817, 2025). "SOX18 is associated with advanced tumor progression and considerably influences tumor cell regulation." (PMID 39791369, 2025). "In experimental tumor models, Sox18 deficiency or COUP-TFII inactivation has been shown to cause reduced tumor lymphangiogenesis and metastasis." (PMID 24286034, 2013). "Furthermore, SOX18 has been implicated in cancer‐related lymphangiogenesis, and its suppression has shown promise in inhibiting tumor metastasis." (PMID 39791369, 2025). "Moreover, SOX11 and SOX18 are closely associated with tumor TMB and NEO, which is of significant importance in predicting immune efficacy and patient prognosis, providing new treatment strategies for personalized immunotherapy." (PMID 38331879, 2024). "Besides, the transcription factor SOX18 has now been implicated in malignant tumor phenotype, angiogenesis, and lymphangiogenesis." (PMID 36959792, 2023). "As the SOX18 expression level is associated with patient survival, inhibition of SOX18 in tumor tissues may provide an effective therapeutic strategy." (PMID 26151573, 2015). "In addition, tumor metastasis was previously found to be inhibited in SOX18-deficient mice and dominant-negative SOX18 shows an inhibitory effect on the migratory ability of MCF-7 cells." (PMID 26151573, 2015). "In contrast, SOX17 and SOX18 exhibited pronounced nuclear and endothelial expressions in tumor tissues, with SOX17 particularly enriched in LUAD and SOX18 in both LUAD and LSCC." (PMID 41373817, 2025). "SOX18, a critical regulator of angiogenesis during embryonic development, appears repurposed in the tumor setting to facilitate neovascularization and stromal remodeling." (PMID 41373817, 2025). "This spatial trend is consistent with SOX18’s involvement in angiogenesis and vascular remodeling within the tumor microenvironment." (PMID 41373817, 2025). "Across both NSCLC subtypes, SOX18 promoter methylation was clearly elevated in surrounding lung tissues compared to tumor cores." (PMID 41373817, 2025). "Another significant finding in PDAC research is the role of microRNA miR-7-5p, which acts as a tumor suppressor by targeting SOX18, a transcription factor involved in angiogenesis and EMT." (PMID 39869563, 2025). "The positive correlation between SOX18 and MEF2C in LUAD, and the strong endothelial co-expression of SOX18 with VCAM1, suggests a coordinated transcriptional module possibly orchestrating endothelial activation in tumor-associated vasculature." (PMID 41373817, 2025). "SOX18 shows the most pronounced spatial enrichment, with expression sharply concentrated in the tumor core and extending into the invasive border in both cancer subtypes." (PMID 41373817, 2025). "Spatial transcriptomics revealed SOX18 enrichment at tumor cores and invasive borders, co-localizing with MEF2C, VCAM1, and p-STAT3 in vascular and stromal niches, while SOX30 expression remained low across all tumor regions." (PMID 41373817, 2025). "SOX30, in contrast to SOX17 and SOX18, exhibited suppressed expression at both mRNA and protein levels across tumor regions." (PMID 41373817, 2025). "The varying levels of SOX18 detected in different cancer types underscore the significance of this transcription factor in tumor progression, metastasis, and the formation of blood and lymphatic vessels within tumors." (PMID 39791369, 2025). "SOX18 showed consistent promoter hypermethylation across tumor samples, despite its protein overexpression." (PMID 41373817, 2025).
tumor (continued). "In this context, SOX18 has emerged as a key regulatory node in tumor angiogenesis and immune modulation." (PMID 41373817, 2025). "The downregulation of miR-7-5p in PDAC leads to SOX18 overexpression, promoting tumor progression through enhanced angiogenesis and increased metastatic potential." (PMID 39869563, 2025). "Sm4 inhibition of SOX18 suppresses vascular development in zebrafish, halts both tumor angio- and lymphangiogenesis in a breast cancer model, and diminishes endothelial-specific viral responses." (PMID 38618963, 2024). "Based on the findings above, we infer that SOX11 and SOX18 have an intimate connection with tumor immunity." (PMID 38331879, 2024). "While SOX18 has been found to be overexpressed in tumours, SOX7 and SOX17 have been reported to be downregulated." (PMID 37511076, 2023). "The overexpression of many other amplified genes (e.g., AURKA, HRH3, MIR646, MRGBP, PCK1, PMEPA1, SLCO4A1-AS1, SOX18, TNFRSF6B) is associated with PDAC cell proliferation and tumour growth." (PMID 36289850, 2022). "Known functions of both SOX18 and RASD1 are consistent with our finding, where SOX18 was suggested to be oncogenic while RASD1 was tumor suppressive." (PMID 34830961, 2021). "In the present study, we have extensively examined the formation of tumor vasculature and show that very early upon inoculation, tumors are infiltrated by SOX18 expressing EVP cells that originate from arterial or venous but not from lymphatic beds." (PMID 30604758, 2019). "In the present study, we aimed to explore the expression and effect of SOX18 on tumor cell physiology and interpret the molecular mechanism involved." (PMID 31189744, 2019). "Sox18 is a transcription factor critically required for tumor-induced lymphangiogenesis, and suppressing Sox18 function impedes tumor metastasis." (PMID 31142802, 2019). "Recent research have revealed that miR-7-5p targets SOX18 to inhibit tumor cell proliferation, migration and invasion in PDAC." (PMID 31510100, 2019). "In conclusion, tumor vascularization recapitulates mechanism observed during embryonic development via the activation and expression of sox18 in specific progenitors of endothelial origin that form arterial and venous capillaries but also lymphatics." (PMID 30604758, 2019). "The effect of SOX18 on the expression of oncogenic proteins and tumor suppressors was also examined." (PMID 31189744, 2019). "As an indirect indication of target engagement, we first confirmed the expression of Sox18 in the 4T1.2 tumor vasculature by in situ hybridization." (PMID 28137359, 2017). "Over the years it became increasingly clear that SOX18 protein plays an important role in promoting tumor angiogenesis and therefore emerged as a promising potential target in antiangiogenic tumor therapy." (PMID 26588701, 2015). "SOX18 protein plays an important role in promoting tumor angiogenesis and therefore emerged as a promising potential target in antiangiogenic tumor therapy." (PMID 26588701, 2015). "Interesting findings include that SOX2 regulates the expression of SOX family proteins SOX1 and SOX18, and that SOX2 down regulates BEX1 (brain expressed X-linked 1) and BEX2 (brain expressed X-linked 2), two genes with tumor suppressor activity in GBM." (PMID 21211035, 2011). "SOX18 is a transcriptional regulator of vascular and lymphatic development, and tumor angiogenesis." (PMID 39998898, 2025). "We speculate this may be due to the inhibition of the endothelial SOX18-MVP axis in tumor endothelial cells." (PMID 39998898, 2025). "SOX18 plays fundamental roles in arterial specification, lymphangiogenesis, and tumor angiogenesis." (PMID 38618963, 2024). "However, a study conducted on thyroid cancer cell lines reported that SOX18 acts as a tumour suppressor, indicating the complexity of its activity, which is likely dependent on the molecular context present in particular tumours." (PMID 37511076, 2023).
tumor (continued). "We hypothesize that the inhibition of SOX9 and SOX18 expression by complex C1 can be used to further sensitize the tumor for the conventional therapy." (PMID 35408514, 2022). "SOX18 homodimers and heterodimers regulate endothelial transcription and play fundamental roles in arterial specification, lymphangiogenesis, and tumor angiogenesis." (PMID 34874911, 2022). "Furthermore, SOX18 is an active player during tumor vascularization, and its inhibition can prevent tumor angiogenesis." (PMID 35104803, 2022). "In future investigations, it will be important to determine whether SOX18 is involved in tumor involution." (PMID 35104803, 2022). "In addition, SOX18 has been suggested to be essential in endothelial progenitor differentiation and tumor angiogenesis." (PMID 34728626, 2021). "The opposite pattern of expression of Sox7 and Sox17 and the involvement of Sox18 in tumor vascularization suggests that SoxF family members may have different functions in ECs dependent on the niche, insult, or type of vascular beds." (PMID 31073164, 2019). "Sox18 was reported to be critical for tumor-induced lymphangiogenesis." (PMID 31114004, 2019). "(C) Expression of SOX18 in the vasculature of the tumor as shown by in situ hybridization." (PMID 28137359, 2017). "Sox18-mutant mice show greatly reduced tumor diameter compared to wild type." (PMID 22481918, 2012). "The reexpression of SOX18 on tumor neo-lymphatics (unpublished data) suggests there might be an additional role of SOX18 in controlling tumor lymphangiogenesis." (PMID 22481918, 2012). "These oncogenic features of SOX17 and SOX18 are supported by their significant co-expression with endothelial and inflammatory mediators such as VCAM1 and STAT3, both of which are known to drive tumor-associated angiogenesis, immune evasion, and metastatic potential." (PMID 41373817, 2025). "In addition, SOX18, a transcription factor regulating early vasculogenesis and lymphangiogenesis in the embryo, has been also identified to play a critical role in the initial steps of tumor angiogenesis and subsequent induction of the tumor growth." (PMID 22481918, 2012). "SOX18 upregulates VCAM1 transcription under inflammatory and angiogenic stimuli, suggesting its role in modulating the tumor microenvironment through endothelial activation and immune cell recruitment." (PMID 41373817, 2025). "Mechanistically, collagen promoted VEGFA expression in tumor cells and directly facilitated vessel formation and the proliferation of HUVEC endothelial cells by upregulating SOX18 expression and its transcriptional activity." (PMID 39823457, 2025). "In vitro assays revealed that HUVEC cells exhibited elevated levels of SOX18, ITGA5, and ITGB1 compared to tumor cells and CAFs." (PMID 39823457, 2025). "Specifically, SOX12 transactivated CCL22, which resulted in the accumulation and enhanced activity of CCR4+Tregs within the tumor, whereas SOX18 up‐regulated CXCL12 expression, attracting CXCR4+TAMs and CXCR4+Tregs into the tumor." (PMID 39072947, 2024). "In particular, most of the amplified genes are involved in proliferation and tumour progression in PDAC, such as AURKA, HRH3, MIR646, MRGBP, PCK1, PMEPA1, SLCO4A1-AS1, SOX18, and TNFRSF6B." (PMID 36289850, 2022). "Authors have shown that after knockdown of SOX18 gene in PANC-1 and the SW1990 cell lines, the abilities of proliferation, migration and invasion were inhibited and the tumor growth was suppressed in vivo." (PMID 35408514, 2022). "SOX7, SOX17, and SOX18 belong to the SOXF family and are functionally redundant; moreover, SOX7 deletion in endothelial cells reduces tumor angiogenesis and promotes tumor vascular normalization." (PMID 34728626, 2021). "As in developmental lymphangiogenesis, transcription factors Sox18 and COUP-TFII and the VEGF-C/VEGFR-3/Nrp2 system are utilized by tumor cells to regulate LEC differentiation and lymphatic vessel sprouting, respectively." (PMID 24286034, 2013).